LEP (leptin)
Diseases named in the same sentence as LEP in open-access papers (continued):
Sharing a sentence is not in itself a finding about the gene and the disease.
Obesity (continued). "Leptin was identified to be independently associated with obesity and T2D in this study." (PMID 38541912, 2024). "While both individual supplementations of VD and ω3FA had beneficial effects, co-supplementation was particularly effective in preventing weight gain, reducing TGs, and decreasing Clostridium sensu stricto, which is associated with obesity and leptin production." (PMID 39765737, 2024). "In addition to chronic low-grade inflammation, elevated circulating leptin, deemed hyperleptinemia, is now considered a hallmark of obesity." (PMID 38206766, 2024). "Furthermore, obesity causes hormonal dysregulation manifested in high levels of leptin and low levels of adiponectin, both associated with a higher risk of pancreatic cancer." (PMID 38730578, 2024). "In addition, despite clear obesity (leptin-deficient (ob/ob) 50 g versus control 25 g), adipocytes from ob/ob mice exhibited higher gene and protein levels of TET2 than wild-type (WT) mice." (PMID 38561362, 2024). "Furthermore, our study found Leptin was independently associated with obesity and T2D in AA and LA women." (PMID 38541912, 2024). "Together, these observations and the current findings related to AZGP1 indicate that increasing leptin sensitivity could be a potential therapeutic strategy to combat obesity-associated metabolic disorders." (PMID 38643150, 2024). "Polymorphisms in the LEP gene are linked to obesity and type 2 diabetes development." (PMID 39203789, 2024). "Hence, leptin’s role during this critical developmental period carries significant implications for regulating body weight and influencing the risk of obesity and related comorbidities." (PMID 38786092, 2024). "In children with overweight/obesity, the levels of pro-inflammatory cytokines, particularly IL-5, IL-17A, IL-33, TNF-α, and leptin, were also elevated, which is consistent with previous findings, indicating chronic low-grade inflammation associated with obesity." (PMID 39902293, 2024). "Whilst the complex interplay between obesity and asthma is not yet completely understood, studies in pre-clinical models have revealed that obesity-associated chronic low-grade inflammation and adipokines such as leptin promote inflammation and remodeling of the lungs." (PMID 39902293, 2024). "However, obesity is associated with an elevated level of leptin, which can stimulate hunger, increase food intake and impair metabolism; this exacerbates obesity the latter results in extra body weight gain in the form of adipose storage." (PMID 37090773, 2023). "Obesity is linked to high leptin, yet low adiponectin levels." (PMID 37299461, 2023). "study among patients with diabetes might be the higher leptin level associated with obesity in these subjects." (PMID 36950695, 2023). "However, leptin's tendency for resistance has caused reluctance in developing effective leptin analogs for treating obesity." (PMID 37937009, 2023). "Obesity has been linked with endocrine disruptions such as hyperinsulinemia and excess leptin secretion, which may affect the hormonal regulation of menstrual function." (PMID 37248288, 2023). "Thus, elevated leptin levels in the first trimester of pregnancy in combination with different risk factors such as hypertension, obesity and diabetes mellitus is currently the main adipocytokine to accurately predict severe and early onset pre‐eclampsia." (PMID 36950780, 2023). "Thus, ob/ob mice (leptin deficient) and db/db mice (leptin receptor deficient) are commonly used models of hyperglycemia and obesity." (PMID 37645520, 2023). "Collectively, these results suggest that leptin may be involved in neutrophil airway inflammation in obesity-associated asthma by affecting M1 macrophages, providing a novel direction for studying the pathogenesis of obesity-related asthma." (PMID 37488474, 2023).
Obesity (continued). "We speculate that obesity-associated hyperleptinemia is a likely responsible factor, as leptin may act directly on adrenal glomerular cells to increase CYP11B2 expression and enhance aldosterone production through calcium-dependent mechanisms." (PMID 37049573, 2023). "Maybe a crucial concept in the pathophysiology of obesity –the leading cause of acquired insulin resistance– is that leptin resistance precedes insulin resistance." (PMID 38260129, 2023). "Elevated adipose mass (obesity) is associated with an increased concentration of leptin." (PMID 37237272, 2023). "All the results suggested that the correlation between leptin and M1 macrophages may be related to neutrophil airway inflammation in obesity-associated asthma." (PMID 37488474, 2023). "The increased leptin level is a hallmark of obesity that regulates metabolism, Jak/STAT and Akt signaling pathways, and modulates T cell functions, which may contribute to the severe outcome." (PMID 36857860, 2023). "Additionally, the study showed that obesity was associated with metabolic abnormalities, such as disturbances in blood lipid levels and changes in leptin levels." (PMID 38201884, 2023). "To further investigate whether leptin-deficiency-induced obesity may underlie other mitochondrial adaptations, we studied mitochondrial biogenesis and dynamics." (PMID 38001815, 2023). "In this work, we examined whether rs10487505 was associated with LEP gene expression in AT in a cohort predominantly with obesity and tested its associations with several obesity-related parameters." (PMID 36833305, 2023). "In conclusion, a crucial hallmark for obesity is the development of resistance to leptin." (PMID 37795371, 2023). "Leptin, a hormone released from adipocytes, has also been implicated in obesity and breast cancer." (PMID 37626871, 2023). "In addition, leptin, adiponectin and inflammatory factors also play an important role in the association between obesity and pancreatic cancer." (PMID 36755926, 2023). "While numerous studies have linked OSA with obesity, it remains uncertain whether leptin, a hormone associated with fat, plays a role in the functional and anatomical defects that lead to OSA." (PMID 37593311, 2023). "Elevated blood leptin level is associated with obesity and, at the same time, cardiovascular and metabolic complications may be present, such as hypertension, type 2 diabetes mellitus and leptin resistance, which makes hyperleptinemia a general health concern." (PMID 38015889, 2023). "Notably, both leptin and LepR are frequently altered in many obesity-associated cancers, including lung, breast, ovarian, pancreas, liver, and prostate." (PMID 37650871, 2023). "In addition, due to its mechanism of action, it alleviated insulin and leptin resistance caused by obesity." (PMID 37510734, 2023). "Extreme obesity caused by impaired leptin signaling leads to changes in subchondral bone morphology, but does not increase the incidence of knee OA, suggesting that obesity due to leptin-impaired signaling is insufficient to induce systemic inflammation and knee OA in female C57BL/6J mice." (PMID 37024929, 2023). "Monogenic obesity is caused by variants of only one gene, and several genes have been associated with this type of obesity, such as leptin (LEP), leptin receptor (LEPR), pro-opiomelanocortin (POMC), and melanocortin 4 receptor gene (MC4R), which is the most common form of monogenic obesity." (PMID 38003013, 2023). "We could suppose that leptin might be involved in the dysregulation of pro-inflammatory cytokines in obesity, which is the leading cause of high morbidity and mortality in patients with SARS-CoV-2 infection." (PMID 37240656, 2023). "In addition, AgRP neurons are inhibited by leptin, and leptin-deficient mice and humans both exhibit a severe obesity phenotype." (PMID 37781919, 2023).
Obesity (continued). "Indeed, some forms of monogenic obesity brought on by loss-of-function LEP mutations are associated with severe childhood obesity, hyperphagia, and, frequently, T2DM." (PMID 37512517, 2023). "Considering that some Adcy3 −/− mice display primary leptin resistance, it is tempting to propose that cAMP deficiency may underlie obesity by blunting anorexigenic downstream responses." (PMID 37064917, 2023). "Leptin and adiponectin are associated with appetite and obesity." (PMID 36839173, 2023). "Obese leptin-deficient mice (ob/ob)—a genetic model of severe obesity because of impaired leptin production—fall asleep more frequently than wild-type (WT) mice, possess an overall 24 h increase in total sleep time, and their sleep fragmentation is more elevated." (PMID 37571368, 2023). "The elevated circulating leptin levels associated with obesity are linked to cardiovascular risk." (PMID 37896046, 2023). "The most frequent causes of monogenic obesity are mutations in the genes leptin (LEP), leptin receptor (LEPR), melanocortin 4 receptor (MC4R), proopiomelanocortin (POMC), proprotein convertase subtilisin/kexin type 1 (PCSK1), and neurotrophic receptor tyrosine kinase 2 (NTRK2)." (PMID 37375898, 2023). "The reasons for this are unknown; however, a family history of TC, iodine deficiency, history of radiation exposure, smoking, obesity, and excessive leptin levels have been reported as possible causes." (PMID 37763777, 2023). "In addition, our ethnically homogeneous study unambiguously shows that the onset of severe obesity is ∼3 years earlier in both LEP and LEPR deficiencies compared with the children deficient for MC4R." (PMID 37659411, 2023). "A transgene model for obesity research is the leptin deficient mouse (ob/ob)." (PMID 37034162, 2023). "However, under obesity conditions, leptin resistance develops due to impairments in intracellular signaling pathways associated with leptin receptors and leptin transport across the BBB." (PMID 37175666, 2023). "However, very little literature is available on the epidemiologic association of dementia and obesity with a focus on adiponectin and leptin." (PMID 37363537, 2023). "In addition, the plasma level of leptin was associated with many traits of patients with CP, including higher-grade HI (25.85 vs. 16.95, and p = 0.037), preoperative obesity (29.55 vs. 21.13, and p = 0.035), and female gender (32.77 vs. 16.77, and p < 0.001)." (PMID 37509115, 2023). "LepRb signaling impairment and leptin resistance are believed to cause obesity." (PMID 36512408, 2023). "Obesity may increase airway oxidative stress through obesity-mediated adipokine imbalance associated with higher levels of leptin and lower levels of adiponectin." (PMID 36346545, 2023). "The strongest predictors among the biochemical parameters of obesity risk were insulin and leptin." (PMID 37373485, 2023). "In addition, single-gene mutations, such as abnormalities of the leptin pathways or the melanocortin-4 receptor, are responsible for early-onset severe obesity associated with hyperphagia, physical dysmorphisms, and other possible endocrine dysfunctions." (PMID 36832370, 2023). "Adiponectin exerts beneficial systemic metabolic effects through its actions on adipogenesis, atherosclerosis, insulin sensitivity, and inflammation, while elevated levels of leptin are associated with obesity, leptin resistance, and adverse effects on the heart." (PMID 37768409, 2023). "As obesity is a major risk factor for type 2 diabetes, genetic variations in leptin signalling mediators may have a role in the onset of the disease." (PMID 38198642, 2023). "This may be because, compared to healthy individuals, obesity predicts higher T-cell PD-1 expression, which may be associated with upregulated leptin." (PMID 37266440, 2023).
Obesity (continued). "Furthermore, obesity is linked to a deficiency of macronutrients (i.e., proteins) and primarily micronutrients such as minerals, vitamins, and related hormones (i.e., leptin, insulin, and ghrelin) that play pivotal roles in obesity-associated comorbidities." (PMID 37686839, 2023). "It was, thus, proposed that obesity is often associated with resistance to leptin action." (PMID 37892180, 2023). "Leptin may affect obesity-associated insulin resistance by promoting miR-21 expression in adipocytes." (PMID 36674935, 2023). "Importantly, Cdc42 plays a vital role in cellular processes associated with the insulin and leptin signaling pathways, which are integral elements involved in obesity development if misregulated." (PMID 38068822, 2023). "However, in children and adolescents with asthma, obesity is associated with elevated serum leptin and tumor necrosis factor-alpha levels." (PMID 38292857, 2023). "Thus, our observation that JNJ greatly lowers the mRNA expression levels of leptin, but not adiponectin, further supports JNJ as a novel therapeutic for the obesity remedy and its related diseases linked with leptin overexpression." (PMID 37175792, 2023). "Suggested mechanisms for the association were the enlargement of soft tissue structures surrounding the airways, causing them to narrow as well as the indirect effects of obesity causing decreased lung volumes, as well as leptin resistance, both leading to unstable breathing and OSA." (PMID 37233636, 2023). "The higher frequency of patients with BMI > 25 and their positive association with serum leptin levels observed in this study correlates with the findings reported by other authors, where obesity has been associated with higher disease activity and worse quality of life among RA patients." (PMID 36980434, 2023). "To determine the potential effects of obesity on fructose uptake and metabolism, we employed pound mice, a mouse strain with hyperphagia, and increased caloric intake as a consequence of deficient leptin signaling." (PMID 37238651, 2023). "Obesity, leptin, and metabolic factors were associated with both CWP and low PPTs." (PMID 37559026, 2023). "Collectively, obesity and systemic inflammation are associated with upregulation of immune checkpoints on T-cells, which is partially mediated via the immunomodulatory effects of leptin in pre-clinical tumour models and clinical studies." (PMID 37173907, 2023). "These leptin and leptin receptor-deficient rodent models have provided many useful insights into the underlying molecular and pathophysiological mechanisms of metabolic and cardiovascular diseases associated with obesity and type 2 diabetes." (PMID 36978976, 2023). "Leptin might be a predictor of advanced PCa in patients with obesity, hence, higher leptin is associated with PCa risk." (PMID 38068717, 2023). "Zinc has been associated with obesity and diabetes in recent research, particularly in terms of altered lipid and insulin profiles, oxidative stress, inflammatory processes, insulin resistance, obesity, and serum leptin levels." (PMID 36846698, 2023). "Additionally, maternal HFD has been shown to upregulate CB1 hypothalamic expression in the offspring, which was associated with leptin pathway impairment and increased susceptibility to obesity." (PMID 36969815, 2023). "Indeed, conditions with reduced leptin levels are known to be associated with hunger, e.g. fasting, or obesity development, e.g., leptin deficiency." (PMID 37069175, 2023). "In this study, the serum LEP level increased in high‐fat diet‐induced obese mice and the intervention of the tested substance downregulated the serum LEP level, suggesting that the tested substance could alleviate LEP resistance caused by obesity." (PMID 37181308, 2023).
Obesity (continued). "In the setting of obesity and advancing age, microglia activation is commonly observed in the hypothalamus, which has been linked to neuronal endoplasmic reticulum stress, declines in insulin and leptin sensitivity, and faster aging in male and female mice." (PMID 37425648, 2023). "Therefore, leptin deficiency in humans and mice causes obesity through the disruption of these processes." (PMID 37547309, 2023). "Conversely, dysregulated DNA methylation has been implicated in the pathogenesis of obesity because it may lead to leptin resistance through hypomethylation of POMC." (PMID 37899888, 2023). "For example, leptin, a product encoded by the obesity gene, is produced primarily by adipocytes." (PMID 37073893, 2023). "Therefore, in the present study, we wanted to investigate the effect of fish protein intake in the black and tan, brachyuric (BTBR) ob/ob mice, which are leptin-deficient and spontaneously develop obesity but are hypotensive when compared to wildtype BTBR." (PMID 37550593, 2023). "Furthermore, obesity is associated with serum copper elevations (~15% higher than controls), with serum copper positively correlating with leptin, insulin, and leptin/BMI ratio." (PMID 35138503, 2023). "Obesity-associated factors, particularly leptin, reduced the anticancer activity of AdipoRon." (PMID 37893166, 2023). "The presence of these polymorphisms may contribute to leptin resistance and, therefore, to obesity and metabolic syndrome." (PMID 37978555, 2023). "Leptin is produced proportionally to the amount of body fat, and in patients with obesity there is an association of high leptin levels with cardiometabolic factors and metabolic syndrome, while high levels of adiponectin are associated with a better metabolic profile in these patients." (PMID 36967781, 2023). "Given that leptin dysregulation is associated with obesity and that high-fat diet impedes neurogenesis, our study underlines the importance of designing future studies to investigate the roles of SOCs in the context of metabolic disorders, especially obesity." (PMID 37361995, 2023). "Therefore, it is necessary to investigate the explore association of ADP and LEP with different obesity phenotypes." (PMID 37853077, 2023). "Leptin, encoded by an obesity-related gene, is mainly secreted by adipocytes." (PMID 37488474, 2023). "Leptin has a pro-inflammatory effect and a high level of leptin causes other inflammatory cells to stimulate the differentiation of monocytes into macrophages, favoring the chronic inflammatory state associated with obesity." (PMID 37361533, 2023). "Taking into account that leptin increases in overweight subjects and subjects with obesity, this association could suggest the development of fatty liver in the subjects with obesity in the present study." (PMID 38137540, 2023). "When LEP levels rise, LEP receptors decrease, leading to LEP resistance, a risk factor for obesity." (PMID 37181308, 2023). "On the other hand, obesity is linked to elevated leptin levels." (PMID 38201918, 2023). "This suggests that leptin may mediate the progression of depression in obese individuals or be a common mechanism causing depression and obesity." (PMID 37387537, 2023). "Leptin can cause liver fibrosis, particularly in those with type 2 diabetes and obesity." (PMID 36985782, 2023). "PRMT2 is associated with disorders of energy metabolism, obesity resistance and leptin sensitivity." (PMID 37144154, 2023). "This suggests that obesity may be caused by either leptin deficiency or genetic defects in the leptin receptor itself." (PMID 38139229, 2023). "Hence, hyperleptinemia and high FFA from increasing the STAT3 phosphorylation in SMCs impairs the leptin signaling pathways during the development of diet-induced obesity, which is associated with disorders of energy homeostasis due to diet-induced obesity." (PMID 36978976, 2023).